CD4 (CD4 molecule)
Diseases named in the same sentence as CD4 in open-access papers (continued):
Sharing a sentence is not in itself a finding about the gene and the disease.
Stroke (continued). "Surprisingly, this experiment also revealed that the infiltration of B-lymphocytes within the infarct at 7 weeks post-stroke is significantly increased in MHCII−/− and CD4−/− mice compared to WT mice." (PMID 32956832, 2021). "Among T-cells, increased expression of CD4+ CD25+ FoxP3+ Treg cells and CD4+ CD28− T-cells are noticed in stroke patients." (PMID 34502395, 2021). "Some studies have shown that both CD4+ and CD8+ T-cells are recruited within 24 h of stroke, whereas other studies have shown a similar activity happens after 4 days of stroke." (PMID 34502395, 2021). "We then compared the B-lymphocyte response to stroke in WT, MHCII−/−, CD4−/−, and MyD88−/− mice to determine if B-lymphocytes mature into IgA + PCs through a T-lymphocyte and MyD88 dependent mechanism." (PMID 32956832, 2021). "The expression level of p-STAT4 signal increased in CD4 T cells, CD4 Tem cells, CD8 Tem cells, B cells, Tregs, NK cells, cDCs and monocytes was dramatically increased after stroke." (PMID 34094644, 2021). "Both the CD4+ and CD8+ compartments were rapidly activated by stroke, evidenced by the increased proportion of cells expressing CD69, a marker of early T cell activation." (PMID 33205448, 2021). "There are several T cell types, including T helper cells (CD4+), killer T cells (CD8+), regulatory T cells (FoxP3), or γδT cells involved in different pathological processes during stroke." (PMID 33429982, 2021). "The increase in CD69+CD4+ cells was restricted to naive and central memory T cells (TCM), which also inversely correlated with stroke severity, while all memory subsets up‐regulated CD69 in the CD8+ compartment." (PMID 33205448, 2021). "CD4+ and GITR+ T cells were preferentially accumulated at the post-ischemic cortex and mice treated with GITR-stimulating antibodies had increased post-stroke inflammatory responses with increased apoptosis of iNSPCs." (PMID 34831273, 2021). "WT, CD4−/−, and MHCII−/− mice underwent experimental stroke and the number of IgA + PCs present in the infarct at 7 weeks following stroke was quantified by IHC." (PMID 32956832, 2021). "We found that absolute cell numbers of neutrophils (Gr1+), monocytes, CD4+ cells, CD8+ cells, and NK1.1+ cells were significantly increased but CD19+ B cells were decreased at 6 h post stroke compared to controls." (PMID 32843630, 2020). "We found that the expression levels of some chemokines and cytokine receptors, such as CSF1R, CSF1, CCL3, CD4, and CCR2, were significantly different in ki20227-treated stroke mice compared to vehicle-treated stroke mice." (PMID 33177990, 2020). "Patients that die following a stroke (<24 h) show an increased infiltration of neutrophils, B lymphocytes, CD3+ T cells and CD4+ T cells in the infarcted area." (PMID 33173502, 2020). "A distinctive feature of T cells infiltrating the ischemic brain is the CD4 vs. CD8 lymphocyte ratio, which is lower than that observed in the blood, even for stroke patients." (PMID 32719588, 2020). "Pro-inflammatory T cells including CD4-positive, CD8-positive, and γδ-T cells have a deleterious role after stroke." (PMID 33182365, 2020). "Recently, in brain slices from 5 patients with acute middle cerebral artery ischemic stroke, who died within 7–10 days after stroke onset, T cells, including MOG-specific CD4+ T cells were found in the infarct and peri-infarct area close to ischemic neurons." (PMID 31001280, 2019). "In the acute phase of other types of stroke, i.e., intracerebral hemorrhage and brain infarction, a decrease was found in the total lymphocyte count and in counts for the CD3+, CD4+, and CD8+ subsets." (PMID 31046777, 2019). "Naïve CD4+ and CD8+ T cells were also decreased within the first days after stroke, which was attributed in the context of stroke-induced immunosuppression (SIDS) to a possible adaptive mechanism, preventing long-term autoimmune responses." (PMID 31001280, 2019).
Stroke (continued). "We further compared the effect of IL‐2mAb on different T lymphocyte subpopulations (CD3+ T cells, CD4+ T cells, CD8+ T cells) at different time points in the ischemic brain after stroke." (PMID 30444079, 2019). "Our data suggested that splenectomy resulted in a selective and prolonged increase in B cell ratio in lymphocytes and a simultaneously decrease in the frequencies of T cells, including CD4+ Th cells and CD8+ Tc cells after stroke." (PMID 29896434, 2018). "Within 24 hours of onset, the stroke patients showed elevated levels of sCD137 (2.7 pg/ml) and CD137 expression on CD4+ T cells (4.9 ± 3.2%) compared with normal controls (1.1 pg/ml, P < 0.01; 1.3 ± 1.0%, P < 0.01)." (PMID 29697202, 2018). "We speculate that CD4 T cells exacerbate brain injury by activating macrophages, as macrophages outnumber any other inflammatory cells in the ischemic brain; thus, macrophages may be the final effectors for neuronal injury induced by inflammatory response after stroke." (PMID 32832192, 2018). "The percentage of CD3+CD45RA- T cells (p<0.05 by two-way ANOVA), including CD3+CD4+ Th cells (p<0.05 by two-way ANOVA) and CD3+CD8+ Tc cells (p<0.05 by two-way ANOVA) among total lymphocytes after stroke significantly decreased in rats with splenectomy." (PMID 29896434, 2018). "In contrast, our results showed that the TCM population in CD4+ T cells and CD8+ T cells increased early after stroke but decreased after the acute phase of stroke." (PMID 30013463, 2018). "Here we examined brain infiltration of CD4+ T, CD8+ T, and NK cells in post-mortem brain sections from ischemic stroke patients who died within 7–14 days after stroke onset." (PMID 29246244, 2017). "CD4+ T cells, together with CD8+, γδ-T cells, and Tregs, change their peripheral pattern following stroke." (PMID 28373915, 2017). "(C) Bar graphs summarize the cumulative data for quantifying CD4+ T, CD8+ T, NK, and B cell counts from brains of ET-1 model at 14 days after stroke." (PMID 29246244, 2017). "AM1241 slightly reduced CD4 and CD8 lymphocyte infiltration in the peri-lesioned area but failed to alter brain infarction, neurological deficits and IBA1 mRNA expression in stroke brain." (PMID 26186541, 2015). "By all methods B2M expression was significantly increased in whole blood in the delayed phase of stroke and CD3E was significantly increased in CD4 cells." (PMID 25090612, 2014). "CD4+ regulatory T cells are upregulated following stroke and CD8+ regulatory T cells are known to suppress CD4+ and CD8+ T cell proliferation and IFNγ production by secreting IL-10." (PMID 25309326, 2014). "Even if the T-cells (CD4+ and CD8+ T-cells) demonstrate an increase in expression of PD-L2 after stroke, the level of expression is only a fraction compared to that of PD-L1 on T-cells." (PMID 25157219, 2014). "Direct detrimental mechanisms elicited by αβ T cell in stroke pathophysiology include CD8+ T cell derived perforin mediated cytotoxicity and IL-21 secreted by CD4+ T cells." (PMID 25414640, 2014). "Tian Zhang from Andreas Meisel`s laboratory in Berlin focused on the effects of late CD4+ T cell depletion on vascular remodeling and clinical outcome in a murine MCAO stroke model." (PMID 24330587, 2013). "Numbers of total peripheral blood mononuclear cells (PBMCs) or splenocytes and lymphocyte subsets, including T cells, CD4+ or CD8+ T cells, B cells and monocytes in the blood and spleen, were decreased after stroke in WT rats." (PMID 23555048, 2013). "The CD4+/CD8+ ratio did not change significantly at the time after stroke or when compared to the control group." (PMID 40342517, 2025). "Thirdly, this study did not explore other CD4+ T-cell subsets in stroke patients as well as their correlation with ATG5, such as Th9 and Th22 cells." (PMID 38511768, 2024). "The inflammatory response is present throughout stroke onset and functional recovery, in which CD4 + T helper(Th) cells play a non-negligible role." (PMID 37884768, 2024).
Stroke (continued). "As healthy controls were enrolled for comparing the expression of ATG5 with stroke patients, CD4+ T-cell subsets of healthy controls were not determined." (PMID 38511768, 2024). "Human studies have evaluated partial cellular infiltration in areas of liquefied necrosis (i.e., weeks to months) in aged stroke brains and found that CD68+ macrophages, T cells (CD4+ and CD8+ cells), and B cells (CD20+ cells) were all present at the infarct site." (PMID 37728582, 2024). "Very recently, an experimental study in a murine model of stroke demonstrated that γδ T cells, rather than CD4+ Th17 cells, serve as a principal source of IL-17A in the injured brain and lung following stroke." (PMID 38965622, 2024). "Second, the test data such as viral load and CD4 index and the lack of characterization of stroke pathology were not collected." (PMID 37770849, 2023). "HIV-Stroke patients with CD4 + counts results (using CD4 count as a proxy for “newly diagnosed”) showed no significant change in clinical presentation severity (NIHSS) (15.9, SD 7.4, p 0.598) and mortality (61, SD 46.3, p = 0.306)." (PMID 37523881, 2023). "Challenges in obtaining other investigations to confirm stroke sub-type and inability to perform HIV testing and CD4+ cell counts for a large proportion of patients significantly impact the chances of comprehensively analyzing the relationship between stroke and HIV." (PMID 37523881, 2023). "Here, we show that CXCL13 is upregulated on inflamed vascular cells, and that during reperfusion, IL-21 producing CD4+ ICOS-1+ CXCR5+ TFH cells are recruited to the brain where they can induce caspase-mediated neuronal death and potentiate secondary stroke damage." (PMID 35624463, 2022). "Neither stroke nor deletion of Bim affected the number of circulating myeloid cells, neutrophils, Ly6Chi monocytes, CD4+ T cells, or FoxP3+ T cells." (PMID 35149957, 2022). "Peripheral blood of stroke patients showed significantly elevated levels of DNAse-I (p < 0.001), LDG (p = 0.003), CD4 (p = 0.005) as well as the pro-inflammatory cytokines IL-17 (p < 0.001), INF-γ (p < 0.001) and IL-22 (p < 0.001) compared to controls, reflecting a TH1/TH17 response." (PMID 35596126, 2022). "In conclusion, we found that stroke could occur among HAART-naive PLWH, distributing in different CD4 levels and age groups." (PMID 34983408, 2022). "Taken together, the data show an accumulation of immune cells in the IC-ANV including dendritic cells and CD4 T-cells, which neighbor the CD31+/CD34+ endothelial tip cells and therefore might support post-stroke angiogenesis." (PMID 35626695, 2022). "Additionally, IFN-γ in the brain released post-stroke can increase MHC II expression in endothelial cells and astrocytes to prime CD4+ T-cells." (PMID 34502395, 2021). "In the current study, we only observed a nonsignificant increase in CD4+/IL-17+ at 4 weeks post-stroke, suggesting that IL-17 does not play a major role beyond the acute phase of stroke." (PMID 33572986, 2021). "We discovered that the delayed infiltration of B-lymphocytes and IgA + PCs into the infarct following stroke can occur independently of CD4 T-lymphocyte help, and that IgA + PC maturation following stroke does not require MyD88 signaling." (PMID 32956832, 2021). "The CD4/CD8 ratio represents a predictor of age-related diseases and non-HIV-associated events (e.g., ischemic heart disease, stroke, and chronic kidney failure and higher mortality." (PMID 33932187, 2021). "Yan's study showed that the percentage of circulating Tregs in CD4+ T cells increased at 1, 7, and 21 days after stroke, without significant correlation with stroke severity." (PMID 33470530, 2021). "On various stroke models, transgenic animals lacking T cells, or animals with antibody-mediated depletion of CD4+, CD8+, or γδT cells presented ischemic damage reduction compared to corresponding WT." (PMID 33429982, 2021). "Autoreactive CD4+ and CD8+ T-cells, as well as B-cells, were increased 4 days after stroke." (PMID 34502395, 2021).
Stroke (continued). "IHC at 7 weeks following stroke revealed no decrease in the number of B220 + B-lymphocytes within the infarct of the CD4−/− and MHCII−/− mice." (PMID 32956832, 2021). "Depletion of CD4+ T cells 3 days post-stroke induction improved behavioral outcomes without affecting infarct size, through the reduction of inflammatory cytokines such as IFN-γ and IFN-γ-inducible protein (IP-10)." (PMID 33173502, 2020). "Additionally, infiltrating cells such as CD4+ and CD8+ T-cells were found in the peri-infarct region of rodents 1 month after stroke in a transient occlusion model." (PMID 33551749, 2020). "It has been found that, during the acute phase of post-stroke neuroinflammation, CD4+ and CD28 null populations are more numerically represented and significantly predominate when the etiopathogenesis of stroke is cardioembolic compared to lacunar or LAAS subcategory." (PMID 33317034, 2020). "In the present study, we found that the expression of IL-17A was increased at 24 h in the lung tissue after stroke, which was mainly derived from γδ T cells, but not from CD4+ Th17 cells." (PMID 31447768, 2019). "Lymphocyte infiltration after experimental stroke has been suggested to take place as early as 3 h for CD8+ T cells and 24 h for CD4+ T cells, while other publications report a delayed peak of CD4+ T cells at 3 days or 5 days." (PMID 31001280, 2019). "In our study, we reported higher serum levels of IL-6 and TNF-α and higher percentage of peripheral CD4+ cells and CD4+CD28 null in subjects with acute ischemic stroke in comparison with subjects without stroke." (PMID 30995924, 2019). "Second, CD4 T cell deficit does not significantly alter p-PTEN protein levels after stroke compared with WT mice, but it significantly enhanced P-Akt protein levels." (PMID 32832192, 2018). "CD4+ helper, CD8+ cytotoxic, and γδT cells play detrimental roles in various stroke models." (PMID 30131754, 2018). "Moreover, in our previous research, we found a dramatic reduction in the percentage of circulating T cell subsets (including CD4+ T cell, CD8+ T cell, and NKT cells) after stroke, which was ameliorated by RIPC after stroke." (PMID 29807548, 2018). "In addition, stroke resulted in increased phosphorylated PTEN, Akt, PRAS40, P70S6, and S6 protein levels in WT mice, which were further enhanced in the animals whose CD4 T cells were impaired." (PMID 32832192, 2018). "We found significantly increased CD4+ T, CD8+ T, NK cells in stroke models compared with sham mice." (PMID 29246244, 2017). "We conclude that CMV seropositivity is linked to a higher incidence of CHD in octogenarians and that senescence in both the CD4 and CD8 T‐cell compartments is a predictor of overall cardiovascular mortality as well as death from myocardial infarction and stroke." (PMID 26696322, 2016). "In a prospective cohort, CD4 + FoxP3+ cells and not CD4 + CD25 + FoxP3+ cells were independent predictors of acute myocardial infarction whereas no relation was found with stroke." (PMID 26822994, 2016). "The proportion of CD4+ T cells to total lymphocytes was not significantly altered in this stroke patient cohort, indicating that CD4+ T cells are lost in a similar quantity from peripheral blood as CD4− lymphocytes." (PMID 27073295, 2016). "Our results demonstrate that treatment with either quiescent or activated CD4/CD8 T cells or activated CD11b+ cells does not significantly increase infarct volume when administered 24 h prior to the onset of stroke in splenectomized mice." (PMID 26634148, 2015). "Given previous reports on the importance of T cells in stroke, we were surprised that adoptive transfer of either CD4+ or CD8+ before MCAO does not exacerbate stroke in male splenectomized mice, or in female mice." (PMID 26634148, 2015). "Thus, we tested the effect of CD4+ and CD8+ transfer 24 hours before MCAO on stroke injury in splenectomized male and female mice." (PMID 26634148, 2015).
Stroke (continued). "In addition, another study demonstrated that adoptive transfer of IL-10-producing B cells into the stroke mice could increase the expression of PD-1 in peripheral CD4+ T-cells, suggesting that PD-1/PD-L1 interaction might also be important in regulatory B cell-provided neuroprotection after stroke." (PMID 25232304, 2014). "We found no significant changes after stroke in either CD8+ cells or CD4+CD25+ T cells, which will largely consist of Tregs." (PMID 25477780, 2014). "While FoxP3+CD25+CD4+ Tregs have beneficial effects after stroke, we should not ignore their possible detrimental effects." (PMID 23983771, 2013). "Recently, several findings do not support the neuroprotective effects of FoxP3+CD25+CD4+ Tregs in stroke treatment." (PMID 23983771, 2013). "Furthermore, stroke also resulted in significantly reduced CD8+ T cells, NK cells and B cells in the spleen, and with insignificantly-reduced T cells, CD4+ T cells and monocytes in the spleens of nude rats that received splenocyte adoptive transfer." (PMID 23555048, 2013). "One study demonstrated that depletion of FoxP3+CD4+ Tregs by utilizing diphtheria toxin prior to stroke induction failed to reduce infarct volume at 96 hours after MCAO and reperfusion injury." (PMID 23983771, 2013). "Like in PBMC, in the ratios of CD4+/CD8+ T cells and Foxp3+/Foxp3− in CD4+ cells were not changed in the spleen in WT rats after stroke." (PMID 23555048, 2013). "While several groups could meanwhile confirm that CD4+ and CD8+ T cells act detrimental during the acute phase of stroke, the contribution of other T cell subsets, in particular regulatory T cells (Treg), remains controversial." (PMID 22883324, 2012). "Taken together with the overall group-level results, the data indicate a consistent immune profile between CeAD patients with and without stroke, characterized by a tendency toward elevated CD4 + T cells and lower NKT-cell frequencies relative to healthy controls." (PMID 41570020, 2026). "Thus, we aimed to observe the quantitative changes of circulating CD4+, CD8+, double-negative T cells, and the CD4+/CD8+ ratio in stroke and SAI." (PMID 40342517, 2025). "Recently, a decreased number of CD8+ T cells, with no changes in CD4+ T cell numbers, was observed in stroke patients with a history of HT and a decreased number of CD8+ T cells in patients with HT from the control group in comparison to patients without HT diagnosis." (PMID 40342517, 2025). "Considering the biological role of peripheral immunosuppression and questioning whether it diminishes the deleterious effect of post-stroke systemic inflammation, we aimed to observe the quantitative changes in CD4+ T cells, CD8+ T cells, and DNT, as well as the CD4+/CD8+ ratio, in stroke and SAI." (PMID 40342517, 2025). "Finally, evaluation of the inflammatory Th1 (CD4+IFN-g+) and anti-inflammatory Th2 (CD4+IL4+) T-cells also did not reveal a change (count or percentage) in PNU-treated post-stroke mice." (PMID 40012683, 2025). "Cellular quantification at day three post-stroke did not reveal changes in absolute counts (bar graph – left two columns) or percentages (bar graph – right two columns) of CD4 T-cells in either the draining lymph node of the brain (cervical lymph node) or the peripheral immune system (spleen)." (PMID 40012683, 2025). "In young mice, stroke decreased CD4+ cell frequency in non-draining lymph nodes (p = 0.001)." (PMID 35910379, 2022). "However, stroke did not impact the frequencies of CD4, CD8 or TCR‐γδ+ T cell subsets at a hyperacute time‐point." (PMID 33205448, 2021). "Removal of the CD4+ T cell population attenuates apoptosis and enhances neurogenesis, while the elimination of CD25+ T cells, which include Treg cells, impairs functional recovery partly through the inhibition of neurogenesis after permanent experimental stroke." (PMID 33461586, 2021).